IL37 (interleukin 37)
Diseases named in the same sentence as IL37 in open-access papers (continued):
Sharing a sentence is not in itself a finding about the gene and the disease.
fungal infections (4 papers, 2014 to 2025). "Further studies are warranted to elucidate the mechanisms by which IL-37 influences the outcomes of fungal infections." (PMID 41293155, 2025). "In the present study we extend these findings to a live infection model, the murine model of disseminated candidiasis, in which we assessed whether IL-37 hampers the innate immune defense against a fungal infection." (PMID 25620965, 2014).
Guillain-Barre syndrome (4 papers, 2013 to 2021). A spectrum of rare post-infectious neuropathies that usually occur in otherwise healthy patients. "This study aims to investigate the concentrations of plasma and cerebrospinal fluid (CSF) IL-37 in patients with Guillain-Barré Syndrome (GBS)." (PMID 24174711, 2013).
influenza (4 papers, 2019 to 2025). An acute viral infection of the respiratory tract, occurring in isolated cases, in epidemics, or in pandemics; it is caused by serologically different strains of viruses (influenzaviruses) designated A, B, and C, has a 3-day incubation period, and usually lasts for 3 to 10 days. "IL-37 has the potential to alleviate inflammation caused by influenza infection, reduce tissue damage, and improve outcomes by modulating macrophage function and MAPK signaling pathways." (PMID 41293155, 2025). "Translating IL-37 into clinical treatment for influenza involves addressing challenges such as optimizing dosage, selecting appropriate administration routes, and determining the best timing for treatment." (PMID 41293155, 2025). "Exogenous expression of IL-10, IL-37, or GM-CSF in the lungs of influenza-infected mice improved survival and recovery from infection." (PMID 33680987, 2021). "IL-37 shows promise in treating influenza by reducing inflammation and regulating immune responses." (PMID 41293155, 2025). "However, little is known about the function of IL-37 in the influenza-infected murine model, particularly the regulatory role in viral pneumonia induced by A/California/07/2009 (H1N1) infection." (PMID 31736917, 2019).
intestinal inflammation (4 papers, 2017 to 2024). "In pediatric IBD patients, IL-37 protein expression is increased in submucosal lymphoid cells and correlated with histological severity score of intestinal inflammation; another IL-1 family member, IL-18, shows the similar pattern as IL-37 in these patients." (PMID 28420941, 2017).
keloid (4 papers, 2020 to 2025). An irregularly shaped, elevated mark on the skin caused by deposits of excessive amounts of collagen during wound healing. "As mentioned in Khattab and Samir’s research, the IL-37 serum level is negatively related to keloid." (PMID 37692568, 2023). "Keloid severity can be affected by IL-37 serum as an anti-inflammatory or immunosuppressant by inhibiting adaptive and innate immunity." (PMID 37692568, 2023). "This negative correlation indicates that the lower level of serum IL-37, the more keloid severity." (PMID 39799030, 2025). "The IL-37 level was lower in severe keloid patients than in mild keloid patients." (PMID 37692568, 2023). "Thus, IL-37 may have a role in the pathogenesis of keloid owing to its ability to suppress the innate inflammatory immune responses." (PMID 39799030, 2025). "In one study, there was a negative correlation between serum IL-37 level and the keloid severity." (PMID 39799030, 2025).
liver disease (4 papers, 2019 to 2025). "In summary, we show evidence that transgene expression of IL-37 reduces liver inflammation and fibrosis in BDL-, CCl4-, and colitis-associated liver disease in mice." (PMID 33746950, 2021). "Serum IL-37 was tested by ELISA in a clinical cohort and correlated with liver disease severity." (PMID 33746950, 2021). "In conclusion, our findings suggest that variations at the IL-37 gene may be useful as genetic predictive risk factors for HBV infection and HBV-mediated liver disease progression in the Saudi Arabian population." (PMID 31073186, 2019). "Thus, IL-37-dependent mechanisms may represent a future target for the treatment of inflammatory and fibrosing liver diseases." (PMID 33746950, 2021). "As immunity plays a pivotal role in the natural course of HBV, the outcome of the infection, and the pathogenesis of liver disease, the genes encoding inflammatory mediators (e.g., TNF-α, TGF-β, and IL-37) may be prospective candidates to predict the progression of HBV-mediated disease severity." (PMID 31073186, 2019). "Although the role of some members of the IL-1 cytokine family in liver disease has been extensively studied (IL-1α, IL-1β, IL-33), leading to strong arguments favoring these molecules as potential therapeutic targets, the role of the other members (IL-36, IL-37, IL-38) remains to be elucidated." (PMID 31507607, 2019).
Myocardial fibrosis (4 papers, 2016 to 2025). "IL‐37 + TnI‐treated DCs increased Treg cells, reduced myocardial inflammation, alleviated myocardial fibrosis, and improved cardiac function." (PMID 41200280, 2025). "Here, we showed the upregulated levels of plasma IL-37 in DCM patients, and demonstrated the protective role of IL-37 on cardiac dysfunction and myocardial fibrosis in DCM mice." (PMID 38790051, 2024). "Both recombinant IL-37 administration or inducing IL-37 expression alleviated cardiac dysfunction and myocardial fibrosis in DCM mice." (PMID 38790051, 2024). "Furthermore, IL-37 treatment or inducing IL-37 expression alleviated cardiac dysfunction and myocardial fibrosis in the hearts of diabetic mice." (PMID 38790051, 2024). "Similar to IL‐37 treatment, administration of a single injection of IL‐37 plus TnI–treated tDCs in post‐MI mice significantly reduced the infiltration of inflammatory cells, ameliorated myocardial fibrosis, and improved cardiac function." (PMID 27919929, 2016). "Hence, IL-37 ameliorated myocardial fibrosis in infarcted hearts." (PMID 34471467, 2021). "The changes in cardiac function, myocardial fibrosis and mitochondrial injury in DCM mice with or without IL-37 intervention were investigated in vivo." (PMID 38790051, 2024).
prostate carcinoma (4 papers, 2019 to 2025). A carcinoma that arises from epithelial cells of the prostate gland. "Finally, consistent with IL-37b being the most abundant isoform of IL-37, studies investigating tumor expression of the IL-37 splice variants identified IL-37b as the isoform expressed by breast, liver, lung and prostate cancer, with low levels of IL-37b significantly associated with poor prognosis." (PMID 31231372, 2019). "IL-37, when combined with radiation therapy (RT), enhanced RT-induced inhibition of cell proliferation and apoptosis in prostate cancer cells." (PMID 40444012, 2025).
acute myeloid leukemia (3 papers, 2022 to 2023). Acute myeloid leukemia (AML) is a group of neoplasms arising from precursor cells committed to the myeloid cell-line differentiation. "Low levels of IL-37 in the sera of patients with acute myeloid leukemia (AML) were shown to be associated with poor prognosis of the disease, but they were restored to normal in complete remission." (PMID 36551790, 2022). "Acute myeloid leukemia (AML) individuals exhibit lower levels of serum IL-37 compared to controls, which correlates with unfavorable prognosis, and they are restored in complete remission." (PMID 37298214, 2023).
allergic bronchopulmonary aspergillosis (3 papers, 2014 to 2024). Allergic bronchopulmonary aspergillosis (ABPA) is a rare immunologic pulmonary disorder caused by hypersensitivity to Aspergillus fumigatus, clinically manifesting with poorly controlled asthma and recurrent pulmonary infiltrates. "To evaluate the potential for IL-37 to limit inflammation also in Aspergillus allergy, we resorted to a murine model of allergic bronchopulmonary aspergillosis (ABPA) in which both the Th2 and Th17 cell responses contribute to the inflammatory response." (PMID 25375146, 2014).
calcific aortic valve disease (3 papers, 2017 to 2024). "Our previous studies found that IL-37, an anti-inflammatory factor, has protective effect against aortic valve calcification." (PMID 38840067, 2024). "Also, a mouse study has showed that recombinant IL-37 treatment reduces osteogenic responses to inflammatory stimuli in human aortic valve interstitial cells and reduces the progression of calcific aortic valve disease." (PMID 28792474, 2017).
cardiac hypertrophy (3 papers, 2016 to 2024). "After age-adjusted analysis, tonsillar hypertrophy was associated with higher tonsillar mRNA expressions of IL-37." (PMID 29942488, 2018).
chronic hepatitis B (3 papers, 2018 to 2021). "In another study, immunobiological factors such as vitamin E, IL-17, IL-37, and IL-38 were assessed in Iraqi male patients with chronic hepatitis B (CHB)." (PMID 34830435, 2021).
coronary artery stenosis (3 papers, 2014 to 2021). "Other studies found that IL-37 in coronary artery stenosis was markedly declined, which was consistent with our observation." (PMID 34580597, 2021).
cystic fibrosis (3 papers, 2014 to 2022). Autosomal recessive disorder caused by pathogenic variants in the CFTR gene (cystic fibrosis transmembrane conductance regulator), which encodes a chloride and bicarbonate channel expressed in epithelial cells, and follow the diagnosis criteria. "To evaluate the anti-allergic activity of IL-37 in a clinically relevant model, we resorted to Cftr tm1Unc (Cftr−/−) mice that are considered to mimic, to some extent, the airway inflammation and infection of human cystic fibrosis." (PMID 25375146, 2014).
eosinophilia (3 papers, 2023 to 2025). "IL-37 treatment reduced allergic symptoms, eosinophilia, and Tfh2 cell proportions, while these effects can be reversed by anti-IL-18Rα." (PMID 40427088, 2025).
gallbladder cancer (3 papers, 2020 to 2025). "In gallbladder cancer, IL-37 was reported to suppress migration and invasion by inhibiting HIF-1α-induced epithelial–mesenchymal transition." (PMID 40444012, 2025). "This aligns with findings in gallbladder cancer where IL-37 suppressed migration and invasion." (PMID 40444012, 2025). "It was also observed that in gallbladder cancer cells transfected with pcD-NA3-IL37, CoCl2 processing stabilized the expression of HIF-1α and inversely regulated the function of IL-37, GBC-SD and NOZ cells still remained a high migration capability simultaneously." (PMID 37928545, 2023).
gestational diabetes mellitus (3 papers, 2021). "Furthermore, IL-37 subtypes and genetic variants follow distinct underlying mechanisms, and miRNAs are also involved in the regulation of the inflammatory response via IL-37 in gestational diabetes." (PMID 34248996, 2021). "Data on miRNAs-mediated IL-37 regulation are scarce: very recent results obtained in women with a diagnosis of gestational diabetes mellitus showed that miR-657 modulates IL-37, influencing the inflammatory response." (PMID 33902634, 2021).
heart failure (3 papers, 2017 to 2021). Inability of the heart to pump blood at an adequate rate to meet tissue metabolic requirements. "We believe that the increase in plasma IL-37 is associated with inflammation, cardiac remodeling, and acute cardiovascular events in heart failure patients." (PMID 28781417, 2017). "In this study, we found that baseline IL-37 levels in patients with heart failure negatively correlate with LVEF while positively correlating with NT-proBNP and hs-TnT, the two most extensively studied biomarkers in evaluating the severity of cardiac function." (PMID 28781417, 2017). "Therefore, a prospective trial consisting of a larger number of patients with heart failure and longer period of follow-up needs to be performed to clarify the significance of circulating IL-37 levels in heart failure." (PMID 28781417, 2017). "However, there is limited information about the role of novel cytokine interleukin-37 (IL-37) in heart failure." (PMID 28781417, 2017). "However, the level of plasma IL-37 in heart failure has yet been investigated." (PMID 28781417, 2017). "We found that plasma IL-37 levels are significantly increased in patients with CHF and that the increase in plasma IL-37 levels is an unfavorable prognosis for patients with heart failure." (PMID 28781417, 2017).
hyperglycaemia (3 papers, 2021 to 2024). "While the mid tertile of IL–37 was associated with higher odds of hyperglycemia (p < 0.01) and low HDL-c (p < 0.05), which was statistically significant in all models." (PMID 38255771, 2024). "For IL–37, the highest tertile was associated only with hyperglycemia (p < 0.01) and this was statistically significant in all models." (PMID 38255771, 2024). "It was found that IL‐37 was significantly associated with a decrease in hyperglycemia‐induced podocyte inflammation, indicating the protective effects of IL‐37 against podocyte injury." (PMID 36757903, 2023). "In addition, IL‐37 was significantly associated with a decrease in oxidative stress and apoptosis induced by hyperglycaemia." (PMID 36757903, 2023). "In addition to direct regulation of the immune system, IL-37 is also correlated with insulin sensitivity, which could contribute to the uncontrolled hyperglycaemia status in GDM women." (PMID 34513891, 2021).
injury (3 papers, 2018 to 2022). Damage inflicted on the body as the direct or indirect result of an external force, with or without disruption of structural continuity. "In addition, the activation of p38MAPK and JNK signaling pathway is an important mechanism of I/R liver injury, and IL-37 may inhibit the activation of p38MAPK and JNK signaling pathways, thereby reducing the release of inflammatory cytokines and improving liver damage." (PMID 29805973, 2018).
leukemia (3 papers, 2021 to 2025). A malignant (clonal) hematologic disorder, involving hematopoietic stem cells and characterized by the presence of primitive or atypical myeloid or lymphoid cells in the bone marrow and the blood. "A few studies utilized human leukemia cell lines transfected with miR-657 and miR-6869-5p, identifying IL-37 and PTPRO as target genes involved in the anti-inflammatory response." (PMID 40559391, 2025). "Human leukemia E6 Jurkat cells and their empty vector-transduced cells express very little IL-37 at both the gene and protein levels, making them suitable for studying IL-37-induced changes." (PMID 36010641, 2022). "Importantly, these data demonstrate that treating aged mice with recombinant IL‐37 significantly boosts anti‐leukemia T‐cell‐mediated immune responses." (PMID 33480151, 2021). "Importantly, we found that recombinant IL‐37 treatment augments the efficacy of aged CAR T‐cells in murine models of leukemia." (PMID 33480151, 2021). "Importantly, IL‐37‐mediated rejuvenation of aged endogenous T‐cells was also observed in aged chimeric antigen receptor (CAR) T‐cells, where improved function significantly extended the survival of mice transplanted with leukemia cells." (PMID 33480151, 2021).
liver cancer (3 papers, 2016 to 2025). An epithelial or non-epithelial malignant neoplasm that arises from the liver. "We determined that IL-37 expression was significantly associated with tumor size (P=0.046), tumor Barcelona Clinic Liver Cancer (BCLC) staging (P=0.030) and microvascular invasion (P=0.046)." (PMID 27835881, 2016). "In liver cancer cells, IL-37 inhibited IL-6 expression by hindering the STAT3 pathway, thereby inhibiting the inflammatory response of IL-6." (PMID 35741608, 2022). "In the present study, Similar to Zhao's findings, We verified that IL-37 was frequently down-regulated in both HCC tissues and liver cancer cell lines." (PMID 27835881, 2016). "Additionally, IL-37 expression correlated with serum alpha-fetoprotein and tumor size in HCC and paracancerous tissues, showing a negative correlation with NF-κB protein expression in HCC tissues and liver cancer cell lines." (PMID 40444012, 2025).
liver fibrosis (3 papers, 2021 to 2025). "In IL-37 transgenic mice with BDL-induced liver fibrosis, reduced expression levels of early liver fibrosis markers, such as C-X-C Motif Chemokine Ligand 2, were observed, along with decreased collagen deposition and liver fibrosis." (PMID 39995661, 2025). "As a novel anti-inflammatory factor, IL-37 holds promise as a potential therapeutic target for liver fibrosis." (PMID 39995661, 2025). "In a BDL-induced mouse model of liver fibrosis, IL-37 overexpression reduced the inflammatory response and HSCs activation." (PMID 39995661, 2025). "IL-37 mitigates liver inflammation and alleviates liver fibrosis by inhibiting the expression of pro-inflammatory cytokines and chemokines in hepatocytes and KCs, reducing neutrophil activity, and acting directly on hepatocytes." (PMID 39995661, 2025). "A second aim of our study was to determine how IL-37 inhibits the formation of host liver egg granuloma and hepatic fibrosis and its mechanism." (PMID 36002836, 2022). "Both CRP and IL-37 serum levels correlate with Child Pugh (CP) score and are significantly lower in healthy controls than in patients with different extent of liver fibrosis as indicated by Child-Pugh-score." (PMID 33746950, 2021). "To investigate the impact of IL-37 in liver fibrosis induced by obstructive cholestasis, we performed bile duct ligation (BDL) in Wt and IL-37tg mice." (PMID 33746950, 2021). "Since there is a broad range of pathologies inducing liver fibrosis we tested the role of IL-37 in different disease models." (PMID 33746950, 2021). "We suggest that predominantly intracellular IL-37 modulates liver fibrosis in two definite ways." (PMID 33746950, 2021). "In addition to BDL as a model of obstructive cholangiopathy and liver fibrosis, we evaluated the effect of transgene IL-37 in CCl4-induced toxic liver injury and consecutive liver fibrosis." (PMID 33746950, 2021). "Here, we hypothesize that IL-37 not only suppresses liver inflammation but also modulates liver fibrosis by the interaction with Smad3." (PMID 33746950, 2021). "Additionally, another study found that IL-37 promotes macrophages polarization from the pro-inflammatory M1 type to the anti-inflammatory M2 type and downregulates the expression of inflammatory chemokines, thereby inhibiting liver fibrosis." (PMID 39995661, 2025). "However, to our knowledge, no research has linked IL-37 to the function of macrophages in egg granuloma formation and hepatic fibrosis during schistosome infection." (PMID 36002836, 2022). "Subsequently, ELISA, quantitative reverse transcription-PCR, fluorescence-activated cell sorting and western blot were used to analyze whether IL-37 inhibits the formation of liver granulomas and the development of liver fibrosis by regulating the phenotypic transition of macrophages." (PMID 36002836, 2022). "Recent studies have reported that IL-37 inhibits the activation of KCs and HSCs and interferes with TGF-β signaling, thereby reducing liver fibrosis and inflammation levels." (PMID 39995661, 2025). "The results of our study suggest that IL-37-induced AMPK activation through its interaction with SMAD3 results in promotion of the polarization of macrophages to the M2 phenotype and ultimately to the reduction of liver egg granuloma and hepatic fibrosis formation in schistosomiasis." (PMID 36002836, 2022). "Thus, our results indicate that IL-37 induces the polarization of macrophages to the M2 phenotype via promotion of AMPK activation, ultimately reducing the development of liver egg granuloma and hepatic fibrosis." (PMID 36002836, 2022).